OR7G2 (olfactory receptor family 7 subfamily G member 2)
Description:
Odorant receptor.
Synonyms: OST260; OR19-6
Tractability: Small molecule: it belongs to a druggable protein family. Antibody: its Gene Ontology location is reachable by antibodies, with high confidence; UniProt places it where antibodies can reach, with medium confidence; UniProt predicts a signal peptide or a membrane-spanning region.
Gene: Protein-coding gene on chromosome 19 (9,100,407 to 9,107,475, reverse strand). Ensembl gene ENSG00000170923.
Subcellular location: Cell membrane
Pathways (Reactome):
Sensory Perception: Expression and translocation of olfactory receptors; Olfactory Signaling Pathway
Gene Ontology:
Molecular function: olfactory receptor activity; G protein-coupled receptor activity
Biological process: signal transduction; detection of chemical stimulus involved in sensory perception of smell; G protein-coupled receptor signaling pathway
Cellular component: plasma membrane; membrane
Genetic constraint (gnomAD): Loss-of-function variants: 0 observed, 0.16 expected, observed/expected ratio (o/e) 0, 90% interval 0 to 1.88. That is too few expected variants to judge how well the gene tolerates losing a copy. Missense variants: 362 observed, 403.75 expected, observed/expected ratio (o/e) 0.9, 90% interval 0.82 to 0.98. Synonymous variants: 153 observed, 161.54 expected, observed/expected ratio (o/e) 0.95, 90% interval 0.83 to 1.08.
Homologues: Orthologues: dog OR7G6 (75% identical), pig OR7G2 (73% identical), rabbit OR7G2 (71% identical), mouse Or7g27 (70% identical), mouse Or7g16 (67% identical), rat Or7g41 (66% identical), rat Or7g20 (65% identical), mouse Or7g20 (65% identical), mouse Or7g28 (64% identical), rat Or7g16 (64% identical), rat Or7g29 (63% identical), mouse Or7g29 (62% identical). Paralogues in human: OR7G1 (71% identical), OR7G3 (65% identical), OR7A17 (62% identical), OR7A5 (61% identical), OR7A10 (60% identical), OR7C2 (60% identical), OR7D4 (60% identical), OR7C1 (58% identical), OR7E24 (57% identical), OR7D2 (57% identical), OR1J4 (50% identical), OR1E1 (50% identical), and 116 more.